IL7 (interleukin 7)
Diseases named in the same sentence as IL7 in open-access papers (continued):
Sharing a sentence is not in itself a finding about the gene and the disease.
diabetes (25 papers, 2010 to 2025). "In our study, we found that the induction of diabetes was associated with decreased levels of IL-2, IL-7, and IL-4, which reflects perturbations in adaptive immunity." (PMID 35554836, 2022). "STZ-induced diabetes was associated with increased levels of blood glucose, ROS, and IL-6 and decreased levels of IL-2, IL-7, IL-4, and GSH." (PMID 35554836, 2022). "At the same time, IL-7 remains the main driver of B and T cell differentiation and maturation, a process linked to the development of insulin resistance and response to diabetes pharmacotherapy." (PMID 28275660, 2017). "Similarly, diabetes was associated with decreased tyrosine nitrosylation of IL-7, which was associated with diabetic retinopathy." (PMID 35801423, 2023). "Additionally, it has been established that the induction of diabetes in animal models is associated with perturbations in the levels of different cytokines, including IL-2, IL-7, and IL-4, which can perturb adaptive immunity." (PMID 35554836, 2022). "IL-7/M25 treatment of recipient mice starting as early as day 2 after cell transfer shortened the lapse of time until diabetes development to day 11.5 ± 1.0 if only diabetogenic CD4+BDC2.5+ T cells were transferred (P < 0.05)." (PMID 31024566, 2019). "In humans, polymorphisms of the IL-7R alpha were associated with an increased risk of developing the disease, and nonenzymatic glycation of the IL-7R alpha in patients with established diabetes and hyperglycemia appear to affect IL-7 signaling." (PMID 23970924, 2013). "IL-7 uniquely maintains FoxP3+ adaptive Tregs (aTregs), which can reverse diabetes in NOD mice." (PMID 40313966, 2025). "The modulation of IL-7 signaling through IL-7R blockade offers a promising therapeutic approach by promoting immune tolerance, altering the balance of effector and regulatory T cells, and potentially reversing established diabetes." (PMID 40313966, 2025). "In the periodontally healthy sites, the concentrations of IL-4, IL-5, IL-7, and IL-13 were decreased in the diabetes group compared to those in the control group; TGF-β concentrations were also decreased in the control group versus those in the rest of the groups (p < 0.05)." (PMID 37835794, 2023). "Tem cells from anti-IL-7Rα-treated mice were also adoptively transferred in recipient mice without causing diabetes and demonstrating that IL-7-signaling deprivation was related to a state of cell intrinsic tolerance." (PMID 26983628, 2016). "To understand the mechanism underlying the effects of ASCs on CAIA, we examined the serum levels of five cytokines (IL-15, IL-1α, IL-6, IL-7, and TNFα), five diabetes-related hormones (resistin, GIP, GLP-1, ghrelin, and leptin), and adiponectin using multiplex immunoassays." (PMID 26210906, 2015). "However, a recent study reported the existence of diabetes-suppressive IL-17–expressing DCs that were capable of promoting the maturation of IL-7–responsive CD25+ CD127+ Treg cells." (PMID 26636339, 2015). "Moreover, IL-7 accelerates diabetes in NOD mice, while blockade of the IL-7R can reverse diabetes in the same model." (PMID 23970924, 2013). "Two cytokine families that are important in diabetes pathogenesis are interferons (IFN), including type 1 IFNs and IFN-γ, and the common γ chain cytokines, including IL-2, IL-4, IL-7, IL-9, IL-15, and IL-21." (PMID 33343569, 2020). "Correlation analysis showed that IL-2, IL-4, IL-7, EOTAXIN, and IFN-γ concentrations in tears were negatively correlated with duration of diabetes, i.e., the shorter the duration of diabetes the higher the cytokine concentration." (PMID 21203348, 2010). "While the exact mechanisms of IL-7 in pancreatitis are not yet well-defined, it is known that IL-7 regulates T cell function and is involved in various immune-related diseases, including diabetes and PC." (PMID 39958351, 2025).
diabetes (continued). "In our study, obese subjects were selected with metabolic healthy phenotype, including no insulin resistance and no diabetes, which could explain why IL-7 was low and not increased by inflammation." (PMID 27611669, 2016). "Indeed, it has been demonstrated that β-islet cell self-reactive CD4+ T cells were not sufficient, and IL-7-mediated homeostatic proliferation was necessary to induce overt diabetes mellitus." (PMID 24586733, 2014). "Blocking interferons on their own does not prevent diabetes in knockout NOD mice, so we tested whether JAK inhibitor action on signaling downstream of common γ chain cytokines, including IL-2, IL-7 IL-15, and IL-21, may also affect the progression of diabetes in NOD mice." (PMID 33343569, 2020).
lymphoma (25 papers, 2006 to 2025). A malignant (clonal) proliferation of B- lymphocytes or T- lymphocytes which involves the lymph nodes, bone marrow and/or extranodal sites. "This may be due to the fact that lymphoma cells may associate with other cells including stromal cells in the tumor, and the consequent cytokine stimulation (e.g., IL-7) may also trigger proliferation." (PMID 23555235, 2013). "In T cell-dominated tumors (e.g., lymphomas), IL-7 exerts anti-tumor effects by supporting T cell survival and expansion." (PMID 41360767, 2025). "The combination of IL-7 with chemotherapy or immunotherapy has been suggested as a potential therapeutic strategy for improving the treatment response and survival in lymphoma patients." (PMID 38675377, 2024). "To further confirm γc effects in vivo, we crossed γcTg mice with an IL-7-overexpressing animal model that displayed B and T lymphoproliferation, resulting in lymphoma." (PMID 37904191, 2023). "Compared to the control group, patients with SS had increased serum IL-7R levels and elevated IL-7 and IL-7R expression in the labial glands, and IL-7 was related to increased inflammation and lymphoma." (PMID 36389806, 2022). "The role of IL-7 in the pathogenesis of types of lymphoma and leukemia is documented in several studies." (PMID 34925323, 2021). "IL-7’s involvement in neoplasia has been appreciated through studies of IL-7 transgenic (Tg) mice models and human lymphoma patients." (PMID 30373315, 2018). "IL-7 levels were significantly higher in gliomas compared to autoimmune/DM cases (p = 0.0035) and lymphomas (p = 0.0119)." (PMID 30379898, 2018). "7/12 Rag-/- mice receiving OT-I T cells plus IL-7 therapy completely rejected EG7 lymphoma cells demonstrating that IL-7 therapy strongly enhances OT-I-dependent tumor rejection in our experimental system." (PMID 27447484, 2016). "OT-I-reconstituted Rag-/- mice receiving IL-7 therapy rejected SIINFEKL-expressing EG7 lymphoma cells." (PMID 27447484, 2016). "Lesional skin from cutaneous T-cell lymphomas patients can secrete more IL-7, which contributes with the proliferation of lymphoma cells." (PMID 25955647, 2015). "Autoimmune lymphocytic thyroiditis is present in the majority of PTL patients, but cytokines, particularly interleukin 7 (IL-7), play a key role in lymphoma." (PMID 25364417, 2014). "IL-7 has been extensively studied in the treatment of lymphoma." (PMID 38675377, 2024). "Lymphomas are also frequently observed in IL-7 transgenic mice." (PMID 34925323, 2021). "However, IL-7 has inhibitory effects on a variety of cancers, including glioma, melanoma, lymphoma, leukemia, and glioblastoma." (PMID 31915416, 2019). "IL-7 appears to be involved in autocrine circuitries to maintain the growth of lymphoma cells." (PMID 25955647, 2015). "Some more obvious cytokines such as IL-2, IL-6, IL-7, and IL-15 have a direct link with T-cell lymphoma progression, and these cytokines’ expression levels have the potential to be used as biomarkers especially to predict the developmental stage of T-lymphoma tumor cells." (PMID 37746258, 2023). "One study found that IL-7 was able to increase the number of CD4+ and CD8+ T cells and improve the function of these cells in lymphoma patients." (PMID 38675377, 2024). "Correspondingly, supplementation of exogenous recombinant IL-7 markedly amplified and sustained polyfunctional CD4+ effector cells, resulting in improved therapeutic outcome in a mouse lymphoma model." (PMID 28939858, 2017). "In order to address this question, Rag-/- mice lacking the IL-7Rα chain (Rag-/-IL-7R-/-) were reconstituted with OT-I T cells, received IL-7 therapy or PBS and were challenged with EG7 lymphoma cells." (PMID 27447484, 2016). "The tumor specificity of the B16-LX/IL-7 vaccine was further confirmed in vivo, where the B16-LX/IL-7 vaccine controlled B16-F10 tumor growth but failed to inhibit EL-4 lymphoma tumors." (PMID 40957993, 2025).
lymphoma (continued). "It has been uncovered that compared with conventional CD19 CAR-T cells, the combination of IL7 and CCL19 can promote the infiltration, accumulation, and survival of CAR-T cells in lymphoma tissues, further enhancing the antitumor effect of conventional CAR-T cells." (PMID 36189258, 2022). "Additionally, of the non-infectious diseases, gliomas can be distinguished from lymphomas by higher levels of GRO/CXCL1 (p = 0.0476), IL-7 (p = 0.0119), and IL-8 (p = 0.0460)." (PMID 30379898, 2018).
Arthritis (24 papers, 2008 to 2025). Inflammation of a joint. "Additional cytokines of C1 included IL-7 (C1L 0.696) and the anti-inflammatory cytokine IL-10 (C1L −0.863); both have been associated with arthritis." (PMID 37047315, 2023). "TSLP and IL-7 have an additive effect on the production of Th17-cytokines in a human in vitro model, and enhance arthritis in mice linked with enhanced inflammation and immunopathology." (PMID 26110994, 2015). "In contrast to IL-7 administration, antibody neutralization of the IL-7 receptor significantly reduced clinical arthritis severity in association with reduced radiographic joint damage." (PMID 24278766, 2013). "Indeed, injections of IL-7 in arthritic mice cause expansion of T and B cells and increased levels of proinflammatory mediators and intensify arthritis severity and joint destruction." (PMID 24278766, 2013). "Therefore, we studied whether IL-7 in fully immunocompetent mice causes enhancement of experimental arthritis and by which mechanisms, specific for IL-7, this is mediated." (PMID 22676399, 2012). "Blocking IL-7 or IL-7R has been shown to reduce inflammation and bone erosion in animal models of arthritis." (PMID 40313966, 2025). "Anti-TNF therapy, which reduces IL-7R expression in macrophages, has been shown to ameliorate IL-7-induced arthritis, further underscoring the role of IL-7R in inflammatory diseases." (PMID 40313966, 2025). "IL-7-driven arthritis is characterized by an increase in IL-7R+ macrophages, which contribute to disease severity by promoting the differentiation of inflammatory M1 macrophages and bone-eroding osteoclasts." (PMID 40313966, 2025). "It is also worth noting that IL-7-induced proliferation of CD4 T cells induces arthritis in a murine model of RA." (PMID 39554252, 2024). "Recent studies have investigated the action of IL-7 on myeloid cells in inducing arthritis or endothelium recruitment." (PMID 38424167, 2024). "Consistently, blocking IL-7 or IL-7R function can attenuate collagen-induced arthritis monocyte recruitment and osteoclast differentiation." (PMID 36311761, 2022). "Previous studies have shown that, at protein level in early arthritis patients, low IL-7 levels were predictive for progression to RA, particularly in ACPA-negative disease." (PMID 33168080, 2020). "Injections with IL-7 in a collagen-induced arthritis (CIA) model induced increased arthritis severity while administering a monoclonal anti-IL-7R antibody in the same model reduced disease severity." (PMID 26110994, 2015). "We here investigated the effects of simultaneous blocking of TSLP and IL-7 activity in murine experimental arthritis and studied their combined effects in in vitro DC + T-cell co-cultures using RA patient material." (PMID 26110994, 2015). "At day 33, arthritis developed in 93% of the PBS-treated mice (14 of 15) compared with 100% in IL-7-treated mice." (PMID 22676399, 2012). "This study demonstrates that IL-7 strongly increases the severity of arthritis and joint destruction in mice." (PMID 22676399, 2012). "IL-7 significantly increased arthritis severity by 135% ± 46% (days 27 through 33, mean ± SEM) compared with PBS-treated mice." (PMID 22676399, 2012). "Because IL-7 increases T-cell activation, arthritis, and joint destruction in the current autoimmune model, this also suggests that administration of IL-7 to humans should be carefully evaluated." (PMID 22676399, 2012). "Apart from the expression of IL-7 and IL-7R, the immunostimulatory capacities of IL-7 suggest an important contribution of IL-7 in joint inflammation in RA." (PMID 22676399, 2012). "Together, this strongly suggests that IL-7 facilitates arthritis by increasing chemotaxis of leukocytes, together with enhancement of vascular permeability and neovascularization, eventually leading to increased synovitis and tissue destruction." (PMID 22676399, 2012).
Arthritis (continued). "We sought to investigate the capacity of interleukin (IL)-7 to enhance collagen-induced arthritis and to study by what mechanisms this is achieved." (PMID 22676399, 2012). "IL-7 intensifies arthritis severity and joint destruction, accompanied by increased Th1 and Th17 activity." (PMID 22676399, 2012). "On day 33, IL-7-treated mice had significantly higher (P < 0.001) mean clinical arthritis scores (11.3 ± 0.9) compared with PBS-treated mice (mean score ± SEM; 6.5 ± 0.8)." (PMID 22676399, 2012). "Anti-IL-7 antibody not only inhibited CD4+ T-cell proliferation (which was a requirement for the development of arthritis) but anti-IL-7 antibody administration also ameliorated arthritis severity." (PMID 20339519, 2009). "The results suggest a potential role for IL-7 as a factor contributing to cartilage inflammation and destruction in arthritis." (PMID 18289383, 2008). "These IL-7R+ B cells seemed to have a proinflammatory role in arthritis, suggesting that the IL-7/IL-7R system might be a potential drug target." (PMID 33168080, 2020). "It was shown, that IL-7 stimulated IL-7R+ mature B cells act pro-inflammatory (increased clinical score, increased anticollagen type II antibodies) after cell transfer in collagen type II-induced arthritis in DBA/1 mice." (PMID 32308655, 2020). "Several other roles in human and experimental arthritis have recently been defined: IL-7 stimulates the production of proinflammatory cytokines in experimental arthritis, influences ectopic lymphoid neogenesis, promotes osteoclastogenesis, and abolishes the function of regulatory T cells (Treg)." (PMID 31276000, 2019). "Binary regressions showed high significance for below normal IL-7 levels for self-reported maternal family history of arthritis (odds ratio (OR): 7.66, P = 0.006) and a trend for smoking (OR: 3.33, P = 0.068) with no further demographic or clinical associations." (PMID 25533722, 2014). "Lack of IL-7 recovery in CR was associated with increased risk of relapsing and related to familial history of arthritis and possibly smoking." (PMID 25533722, 2014). "IL-7 increased arthritis severity and radiology-assessed joint destruction." (PMID 22676399, 2012). "Together, this indicates that blockade of IL-7 or the IL-7R, preventing IL-7R-induced immune activation by IL-7, might be successful therapeutic strategies to inhibit T-cell-driven inflammation and joint destruction in arthritis." (PMID 22676399, 2012). "Thus, arthritis produced in these mice by the F759 mutation in gp130 required not only homeostatic CD4+ T-cell expansion but upregulation of IL-7 gene expression in nonhemopoietic cells as well." (PMID 20339519, 2009). "Adoptive transfer of adequate ILC2s to arthritis models, in which the isolated cells were expanded in vitro through stimulation using cytokines such as IL-2, IL-7, IL-25, IL-33, and TSLP, mitigated experimental arthritis." (PMID 35163028, 2022). "We also demonstrated that STAT5 is an important mediator of IL-7-induced osteoclast differentiation and suggest the possibility of using JAK/STAT5 as a therapeutic target for arthritis." (PMID 29104576, 2017). "Our group previously demonstrated that IL-7 and TSLP separately play a pro-inflammatory role in experimental murine arthritis." (PMID 26110994, 2015). "In the group of mice with adjuvant-induced arthritis without exposure to any agents, lymphopoetin IL-7 demonstrated the highest degree of deviation from controls, with a 2.5-fold increase by day 10 and subsequent decrease to control values." (PMID 36293292, 2022). "However, we did find bilateral hyperalgesia and raised serum cytokines TNFα, IL-7, and IL6 in arthritis mice." (PMID 32471455, 2020). "Thus, we believe that IL-7, such as TNF-α, IL-6, and IL-1, is a potent factor that can itself induce osteoclasts, suggesting the potential of IL-7 as the “best” therapeutic target for alleviating arthritis by suppressing both inflammation and bone erosion." (PMID 29104576, 2017).
Arthritis (continued). "IL-7 is unlikely to be a sole mediator of cartilage destruction in arthritis." (PMID 18289383, 2008). "Though both IL-7 and TSLP induce T-cell activation and proinflammatory cytokine production via different target cells while signalling through the same receptor subunit, their combined effects have not been studied in arthritis." (PMID 26110994, 2015).
type 1 diabetes (23 papers, 2013 to 2025). "Aberrant expression and functional impairment of IL-7 or other components of the IL-7 signaling pathway are frequently linked to several chronic inflammatory autoimmune disorders, RA and type 1 diabetes being 2 such examples." (PMID 39496049, 2024). "In vivo experiments reported that the release of sCD127 at the onset of Type 1 diabetes was associated with inhibiting IL-7-mediated signaling and cell proliferation." (PMID 29261677, 2017). "As we previously reported, islet transplantation in patients with type 1 diabetes is associated with IL-7-mediated homeostatic proliferation of memory autoreactive T cells." (PMID 26983628, 2016). "Patients at risk for or with diagnosed type 1 diabetes have normal circulating levels of IL-7." (PMID 26983628, 2016). "Headache was the most frequent adverse event in a Phase Ib study that evaluated how the blockade of IL-7 would affect immune cells and relevant clinical responses in patients with type 1 diabetes." (PMID 38022684, 2023). "In this article, we discuss how the IL-7/IL-7R pathway can contribute to the development of type 1 diabetes and how preclinical models have demonstrated the efficacy of a selective targeting of this pathway." (PMID 26983628, 2016). "Increased concentrations of IL-7 and IL-15 have also been found in patients with type 1 diabetes after islet transplantation." (PMID 23970924, 2013). "Other diseases with metabolic alterations, such as autoimmune diabetes, have exhibited high serum sCD127 concentrations at the onset of type 1 diabetes, showing that metabolic factors may contribute to dysregulation of the IL-7/IL-7 receptor pathway." (PMID 29423061, 2018). "IL-7 and IL-15 have been found at elevated levels in the SF from RA and JIA patients, and in the pancreas of murine models of Type 1 diabetes (T1D)." (PMID 27242798, 2016). "We previously demonstrated that long-term blocking of IL-7 signaling, which is critical for the survival and function of T cells, prevented and reversed type 1 diabetes in non-obese diabetic mice." (PMID 28356069, 2017). "Reduced circulating T cell counts have been recently reported also in patients with type 1 diabetes; however, no signs of increased circulating IL-7 or increased homeostatic T cell proliferation have been reported in those patients." (PMID 23970924, 2013).